DNAAF4 (dynein axonemal assembly factor 4)
Description:
Axonemal dynein assembly factor required for ciliary motility. Involved in neuronal migration during development of the cerebral neocortex. May regulate the stability and proteasomal degradation of the estrogen receptors that play an important role in neuronal differentiation, survival and plasticity.
Synonyms: DYX1C1; EKN1; FLJ37882; CILD25; pf23; DYX1; DYXC1; RD
Tractability: Antibody: its Gene Ontology location is reachable by antibodies, with high confidence. PROTAC: ubiquitination databases record sites on it.
Gene: Protein-coding gene on chromosome 15 (55,410,525 to 55,508,234, reverse strand). Ensembl gene ENSG00000256061.
Subcellular location: Nucleus; Cytoplasm; Dynein axonemal particle; Cell projection, neuron projection
Subcellular location (Human Protein Atlas): Cytosol; Mid piece; Connecting piece; Plasma membrane; Principal piece
Gene Ontology:
Molecular function: nuclear estrogen receptor binding; protein binding
Biological process: cilium movement; determination of left/right symmetry; inner dynein arm assembly; outer dynein arm assembly; regulation of intracellular estrogen receptor signaling pathway; regulation of proteasomal protein catabolic process; epithelial cilium movement involved in extracellular fluid movement; heart development; neuron migration
Cellular component: cytoplasm; cytosol; nucleus; dynein axonemal particle; extracellular region; neuron projection
Genetic constraint (gnomAD): Loss-of-function variants: 36 observed, 46.72 expected, observed/expected ratio (o/e) 0.77, 90% interval 0.59 to 1.02. The upper end of that interval is the gene's LOEUF score, 1.02, which puts it in group 4 of 6, group 1 being the genes least tolerant of losing a copy. Missense variants: 572 observed, 497.55 expected, observed/expected ratio (o/e) 1.15, 90% interval 1.07 to 1.23. Synonymous variants: 190 observed, 169.98 expected, observed/expected ratio (o/e) 1.12, 90% interval 0.99 to 1.26.
Gene-disease validity (ClinGen):
ClinGen rates the evidence that DNAAF4 causes each of these diseases.
primary ciliary dyskinesia 25 (autosomal recessive): Definitive.
Homologues: Orthologues: chimpanzee DNAAF4 (99% identical), macaque DNAAF4 (98% identical), rabbit DNAAF4 (90% identical), dog DNAAF4 (88% identical), pig DNAAF4 (88% identical), mouse Dnaaf4 (79% identical), guinea pig DNAAF4 (78% identical), rat Dnaaf4 (74% identical), tropical clawed frog dnaaf4 (56% identical), zebrafish dnaaf4 (54% identical). Paralogues in human: TOMM70 (22% identical), TTC12 (20% identical), UNC45B (16% identical), UNC45A (15% identical), SPAG1 (14% identical), STIP1 (14% identical), TTC1 (13% identical), RPAP3 (13% identical), ST13 (12% identical), TOMM34 (11% identical), STUB1 (11% identical), SGTA (11% identical), and 6 more.
Diseases named in the same sentence as DNAAF4 in open-access papers:
DNAAF4 is named in the same sentence as 30 diseases in open-access papers, as found by Europe PMC text mining. Sharing a sentence is not in itself a finding about the gene and the disease. The quoted sentences say what the papers report.
dyslexia (64 papers, 2005 to 2025). A learning disorder characterized by an impairment in processing written words. "In this line, DNAAF4 was found to be associated with phonological memory in dyslexia as well as with phonological working memory in healthy participants." (PMID 34539327, 2021). "Targeted sequencing of two genes in the dyslexia-risk locus DYX1 on chromosome 15 provides no support for a role for DNAAF4 in modulating performance on any tested trait but does implicate a common variant downstream of CYP19A1." (PMID 40424442, 2025). "Two of the most replicated dyslexia candidate genes are DYX1C1 (DNAAF4) and DCDC2." (PMID 37237337, 2023). "DNAAF4 (formerly known as DYX1C1) is involved in neuronal migration supporting the hypothesis of disturbed migration in dyslexia." (PMID 34539327, 2021). "For DNAAF4, the literature analysis provided a link between dyscalculia and dyslexia." (PMID 34539327, 2021). "Based on rodent models, it has been proposed that DNAAF4 mutation affects neuronal migration in the developing neocortex The link between DNAAF4 and dyslexia requires further confirmation since this gene did not associate with dyslexia in follow-up studies on other populations." (PMID 35873488, 2022). "DYX1C1 (DNAAF4) and DCDC2 are two of the most replicated dyslexia candidate genes in genetic studies." (PMID 37237337, 2023). "We present additional evidence for a role in dyslexia risk for DCDC2, KIAA0319, GRIN2B and CYP19A1, but not for DNAAF4." (PMID 40424442, 2025). "Focusing on dyslexia candidate genes, 33 out of 50 DD candidate genes were detected in NES cells by RNA sequencing, and seven candidate genes were upregulated during differentiation to neurons, including DYX1C1 (DNAAF4), a highly replicated DD candidate gene." (PMID 32445086, 2020).
primary ciliary dyskinesia (11 papers, 2014 to 2024). A rare, genetically heterogeneous, primarily respiratory disorder characterized by chronic upper and lower respiratory tract disease. "Variants in approximately 58 genes cause primary ciliary dyskinesia (PCD) in humans, including the dynein arm (pre)assembly factor (DNAAF) gene DNAAF4." (PMID 38498551, 2024).
male infertility (4 papers, 2019 to 2025). The inability of the male to effect fertilization of an ovum after a specified period of unprotected intercourse. "The deletion of DNAAF4 in mice and mutations in humans cause symptoms characteristic of PCD (chronic airway disease, laterality defects, and male infertility) (CILD25)." (PMID 31817850, 2019). "Therefore, we hypothesize that the significant downregulation of DEGs (CFAP70, TTC29, CCDC40, DNAAF4, SYCE3, STK36, SPI1 and EMX2) in hybrid yellow catfish is the primary cause of male infertility or reduced fertility." (PMID 38891632, 2024).
Infertility (2 papers, 2022 to 2023). "Therefore, we can infer that the DNAAF4 mutation caused infertility in the proband." (PMID 36583018, 2022).
DNAAF4 also shares sentences with these, for which no sentence is quoted: Hydrocephalus (4 papers); situs inversus (4); ciliopathies (3); scoliosis (3); breast carcinoma (2); Kidney Cyst (2); language disorder (2); neuroblastoma (2); type 2 diabetes (2); asthenozoospermia (1); benign tumors (1); breast tumors (1); cancer (1); childhood apraxia of speech (1); deafness (1); Dyscalculia (1); hearing loss (1); intellectual impairment (1); lymph node metastasis (1); major depressive disorder (1); memory (1); neurodevelopmental disorder (1); neurological disease (1); reading disorder (1); schizophrenia (1); tumor (1).